BRCA1 (BRCA1 DNA repair associated)
Diseases named in the same sentence as BRCA1 in open-access papers (continued):
Sharing a sentence is not in itself a finding about the gene and the disease.
breast cancer (continued). "Risk management programs targeting women with genetic predispositions to breast cancer (BC), eg, BRCA1 and BRCA2, are effective assuming full adherence with the program protocol." (PMID 38564263, 2024). "To validate our preclinical findings, we performed pFLT1 and FLT1 immunostaining on tissue specimens that were obtained prior to PARPi treatment from 10 breast cancer patients harboring mutations in the BRCA1/2 or PALB2 DNA damage response (DDR) genes." (PMID 38956205, 2024). "There is evidence indicating the mutations of BRCA1 were the key issue for breast cancer through bioinformatic methods." (PMID 37957856, 2024). "In this study, we identified 12 carriers of PALB2 pathogenic variants in 1556 Chinese patients with BRCA1/2-negative early-onset breast cancer, resulting in a mutation frequency of 0.77%." (PMID 38914840, 2024). "The most prevalent pathogenic variant of the BRCA1 among breast cancer patients was c.2635G > T, while the most common pathogenic variant of the BRCA2 was c.5164_5165del." (PMID 38167124, 2024). "The role of BRCA1 germline mutations in breast cancer prognosis is still debated due to their small proportion and requires further investigation." (PMID 38543119, 2024). "Comparison of the impact of HRT on breast cancer risk in the general population and BRCA1/2 pathogenic variant carriers." (PMID 38892081, 2024). "Olaparib is an oral PARP inhibitor designed for patients with HER2-negative advanced breast cancer who carry germinal BRCA1/2 mutations." (PMID 39606228, 2024). "Subsequently, PARP inhibitors (PARPi) have developed rapidly in clinical trials for ovarian and breast cancers with BRCA1/2 mutations and other HR gene defects." (PMID 39156700, 2024). "The loss-of-function (LOF) classification of most missense variants in tumor suppressor breast cancer genes BRCA1, BRCA2, PALB2, and RAD51C remains unclassified and confounds clinical actionability." (PMID 39430403, 2024). "After a follow-up of 10 years, BRCA1 pathogenic variant carriers who used ET had a significantly lower breast cancer incidence than those who used EPT (12 vs. 22%, p = 0.04)." (PMID 38892081, 2024). "There is a positive correlation between the therapeutic efficacy of PARP inhibitors and platinum-based salts in breast cancer patients with mutations in the BRCA1/2 and HRR genes." (PMID 38397152, 2024). "Firstly, it conducts a literature review and investigates the molecular mechanisms that contribute to the differences in the tumour microenvironment between BRCA1 PV-associated breast cancers and other sporadic breast cancers." (PMID 39682099, 2024). "Among breast cancers of all phenotypes, BRCA1 germline mutations were present in 6–8% and somatic mutations in 3–4%; the BRCA2 germline mutations were in 5–7% and somatic mutations in 2–4%." (PMID 38397152, 2024). "Patient 553 carries the BRCA1 c.5328delC variant and was diagnosed with breast cancer at 32 years old, while she was 18 weeks pregnant." (PMID 39624521, 2024). "Accordingly, restoration of backup OFP in BRCA1-deficient breast cancer cells suppresses gap formation via the loss of 53BP1." (PMID 39594596, 2024). "Such breast cancers tend to exhibit greater aggressiveness and poorer prognoses due to the influence of BRCA1 pathogenic variants (PVs) on the tumour microenvironment." (PMID 39682099, 2024). "Given the critical role of PARP inhibitors in selectively killing tumor cells with HRD features, they have emerged as a promising therapeutic strategy whose indications have been expanded from germline BRCA1/2-mutated to HRD breast cancer." (PMID 39334297, 2024). "Three focus groups (90–110 min) were conducted with 19 breast cancer survivors carrying a BRCA1/2 mutation." (PMID 38192174, 2024). "In the neoadjuvant setting, a single-arm prospective study using cisplatin monotherapy reported a pathologic complete response (pCR) rate of 61% among BRCA1-mutated breast cancer patients." (PMID 39014466, 2024).
breast cancer (continued). "Although susceptibility to breast cancer in BRCA1 and BRCA2 mutation carriers has been known for several decades, mechanisms responsible for this susceptibility are just beginning to be identified, largely due to recent advances in single-cell technologies." (PMID 38059556, 2024). "In certain populations, more prevalence of germline mutations related to breast cancer such as BRCA1, BRCA2 is observed." (PMID 39684874, 2024). "Metastasis of breast cancer occurs more frequently in carriers of BRCA1 mutation, often manifesting as lung metastases and distant lymph node involvement." (PMID 38182557, 2024). "Based on its mutation frequency and disease penetrance, PALB2 is considered as the third major high-risk breast cancer gene alongside BRCA1 and BRCA2, all of which being key factors for the maintenance of genome stability." (PMID 38597967, 2024). "As early as 2014, the FDA approved the utilization of PARPi for treating breast cancer in individuals with BRCA1/2 germline mutations." (PMID 38953104, 2024). "So far, identifying gBRCAm has mainly offered information on cancer risks, notably the risk of breast cancer, with a lifetime risk of 50–70% for patients with pathogenic variants in BRCA1." (PMID 39319938, 2024). "Approximately 2.1–6% of women with breast cancer who undergo genetic testing will carry germline pathogenic variants in BRCA1/2, and 0.2–0.9% are carriers of a pathogenic variant in PALB2." (PMID 38248108, 2024). "We found that the risk for skin cancer was increased after a diagnosis of breast cancer for BRCA1 mutation carriers (HR = 1.77, 95% CI: 1.26–2.50, p = 0.001) but not for BRCA2 mutation carriers (HR = 1.13, 95% CI: 0.76–1.67, p = 0.56)." (PMID 38741145, 2024). "Previous studies have also suggested that the CASP8 D302H polymorphism decreases breast cancer risk associated with BRCA1 and BRCA2 mutations, delaying cancer onset." (PMID 39351539, 2024). "Regarding cancer treatment, preliminary evidence indicates that BRCA1 promoter methylation is associated with sensitivity to a PARP inhibitor in the primary setting in breast cancer while results in metastatic disease are conflicting." (PMID 40225940, 2024). "Genetic susceptibility is responsible for about 5–10% of all breast cancer cases, in which germ-line mutations of BRCA1 account for 50% of them." (PMID 38734703, 2024). "We found that breast cancer susceptibility variants in BRCA1, BRCA2, ATM, and CHEK2 were associated with development of CBC in a subtype-specific manner." (PMID 39786405, 2024). "Single base substitution Signature 3 (SBS Signature3) has been proven to be highly correlated with BRCA mutations and BRCA1 promoter methylation in breast cancer and other tumors." (PMID 39334297, 2024). "This confirms previous findings about high TN breast cancer immunogenicity caused by generally higher aggressiveness of this subtype and due to the higher association with occurrence of BRCA1 and BRCA 2 mutations." (PMID 38711512, 2024). "Reconstitution of Gata3 in Brca1-deficient mammary tumor cells restores the HR efficiency of Brca1-deficient cells and improves DNA damage repair in mammary tumorigenesis." (PMID 38627785, 2024). "Magnetic resonance imaging (MRI) surveillance is offered to women with a pathogenic variant in the BRCA1 or BRCA2 gene who face a high lifetime risk of breast cancer." (PMID 38421676, 2024). "Unexpectedly, MBSR aggravated menopausal symptoms in both BRCA1/2 mutations, especially in breast cancer survivors." (PMID 39201170, 2024). "In contrast, the probability of developing breast cancer in men with BRCA1 and BRCA2 mutations is 1.2% and 8.9%, respectively." (PMID 38543119, 2024). "In the exploration of breast cancer pathogenesis, researchers discovered that the breast cancer susceptibility gene (BRCA1) gene in pigs encodes a nuclear protein consisting of 1863 amino acids, identical to that in humans." (PMID 39204153, 2024).
breast cancer (continued). "In terms of treatment, the OlympiA trial investigated the effectiveness of adding olaparib, a targeted therapy, to standard therapy in breast cancer patients with BRCA1/2 mutations." (PMID 38791944, 2024). "Our results show that the Korean NIC expansion and additional genetic counselor involvement together brought about a significant increase in the number of effective BRCA1/2 mutation tests being provided to newly diagnosed breast cancer patients." (PMID 38791944, 2024). "Most significantly, inherited mutations in the DNA repair genes BRCA1/2 DNA Repair Associated (BRCA1/2) incur a lifetime risk of breast cancer of approximately 50%." (PMID 38542380, 2024). "Consistent with experimental evidence that hCCAR2 knockout renders BRCA1-null cells resistant to DNA damaging agents, BRCA1-deficient breast cancer patients with a low hCCAR2 level have a worse prognosis than those with a high hCCAR2 level." (PMID 38172598, 2024). "The compound was also in synthetic lethality with loss of BRCA1 as demonstrated by its extreme activity in BRCA1‒/‒ syngeneic cells compared to WT cells and in cells with BRCA1 pathogenic mutations (MDA‐MB‐436 breast cancer and COV362 ovarian cells)." (PMID 39492835, 2024). "Considering that about 30% of the enrolled carriers developed breast cancer, these findings emphasize the need for increased awareness about breast cancer surveillance and providing more affordable screening options for BRCA1/2 mutation carriers." (PMID 39590130, 2024). "By implementing these strategies, LMICs can significantly improve breast cancer outcomes and ensure equitable care for all patients, including those with BRCA1/2 germline mutations." (PMID 39421188, 2024). "The cumulative risk of developing breast cancer by age 70 is approximately 55%–70% for individuals carrying BRCA1 mutations and 45%–70% for those carrying BRCA2 mutations." (PMID 39421188, 2024). "The most common histopathological subtype associated with BRCA1-positive breast cancers is typically the “basal-like” or “triple-negative” subtype." (PMID 38674216, 2024). "From the perspective of medical and health systems in China and the US, Talazoparib has high cost-effectiveness in the treatment of advanced breast cancer patients with BRCA1/2 mutations." (PMID 38886516, 2024). "BRIP1 gene was closely related to the function of breast cancer susceptibility BRCA1 (breast cancer 1, early onset), also known as BACH1 or FANCJ, located on 17q22-q24, about 18Kb, composed of 20 exons and 19 introns." (PMID 39211736, 2024). "Breast cancer susceptibility genes BRCA1 and BRCA2 are involved in homologous recombination (HR) and play a pivotal role in the repair of DNA double-strand breaks." (PMID 39014466, 2024). "This study evaluates the cost-effectiveness of talazoparib vs. the physician’s choice of chemotherapy as maintenance therapy for germline BRCA1/2 mutated HER2-negative advanced breast cancer from the perspective of healthcare in China and the US." (PMID 38886516, 2024). "We found that, similar to loss of RAD18, UBC13 and PALB2, loss of RNF168 resulted in an increase in fork stalling in both BRCA1-deficient U2OS cells (Supplementary S4A) and BRCA1-deficient breast cancer MDA-MB-231 cells." (PMID 38943334, 2024). "Individuals with pathogenic PALB2 variants are advised to follow breast cancer risk management protocols similar to those for individuals with BRCA1/2 variants." (PMID 39409938, 2024).
breast cancer (continued). "Women possessing a pathogenic BRCA1 or BRCA2 variant were found to be at an elevated susceptibility to breast cancer, wherein this risk appears to be more pronounced amongst individuals with a first-degree familial background." (PMID 38391399, 2024). "About 3% of breast cancers (about 7500–8500 women per year) and 10% of ovarian cancers (about 2000 women per year) are cases with BRCA1 mutations." (PMID 38790714, 2024). "In Asian populations, studies were done on unselected breast cancer germline mutation spectra, the mutation rates ranged from 1.5% to 2.7% for BRCA1 and 2.4% to 3.8% for BRCA2." (PMID 39272924, 2024). "We conclude that BRCA1-associated breast cancer has a higher rate of overall and nodal pCR than both BRCA2-associated and sporadic disease." (PMID 39060255, 2024). "Numerous breast cancer patients carrying germline mutations in the breast cancer 1 (BRCA1) or BRCA2 genes display specific subtypes of the disease." (PMID 39690423, 2024). "Many studies, including two meta-analyses, showed that prophylactic bilateral mastectomy reduces the risk for breast cancer in unaffected women with BRCA1 [relative risk (RR)= 0.134, 95% CI, 0.019–0.937] and BRCA2 (RR= 0.183, 95% CI, 0.072–0.468)." (PMID 39507757, 2024). "Several studies have demonstrated that loss of HP1α impairs the recruitment of RAD51 and BRCA1 (breast cancer 1, early onset), two HR proteins, that delay DSB repair after irradiation, and lead to radiosensitivity." (PMID 39414799, 2024). "This article summarizes the BRCA1/2 mutation sites, clinical and pathological characteristics, menstruation, and fertility status among breast cancer patients in the Chinese Hakka population." (PMID 38167124, 2024). "Factors that can increase the risk of breast cancer include age, genetic mutations (such as BRCA1 and BRCA2), family history of breast cancer, radiation exposure, obesity, etc.." (PMID 39247188, 2024). "Most patients, who perceive OTC, have breast cancer (45% in our cryobank), which can be caused by BRCA1/2 mutations." (PMID 38332226, 2024). "Studies on BRCA1-mutated breast cancer showed a higher and earlier incidence of brain metastasis, also after controlling for other known prognostic factors such as age, disease stage, and tumor receptor status (ER, PR, HER2)." (PMID 38365640, 2024). "The research demonstrated that the frequency of BRCA1/2 mutations was 17.6% in ovarian and breast cancer." (PMID 39338246, 2024). "The average woman with a germline pathogenic variant in BRCA1/2 has a 69–72% (95% CI 61–79%) lifetime risk of developing breast cancer between the ages of 25 and 80 years old." (PMID 38248108, 2024). "Women harboring germline pathogenic variants (PV) in the breast cancer Type 1 susceptibility gene (BRCA1) have a lifetime risk of breast and high-grade serous ovarian cancer (HGSOC) exceeding 70% and 40%, respectively." (PMID 40225940, 2024). "Data on real-world prevalence and outcomes in patients diagnosed with pathogenic germline variants in BRCA1 or BRCA2 (gBRCAm) breast cancer is sparse." (PMID 39319938, 2024). "This lays the foundation for future prevention and treatment of breast cancer caused by BRCA1 mutations." (PMID 39253075, 2024). "BRCA1/2 are the most important breast cancer predisposition genes, representing 58.3% of all disease-causing variants, which is also in line with findings described in other populations." (PMID 39684258, 2024). "Our data align with the ORR of 62.5% in breast cancer patients with BRCA1/2 mutations treated with talazoparib in the phase 3 EMBRACA trial." (PMID 38010394, 2024). "TNBC accounts for 15–20% of breast cancers, with a substantial percentage displaying a deficiency in BRCA1." (PMID 38256203, 2024). "This economic evaluation examines the cost-effectiveness of adjuvant olaparib therapy in individuals with early-stage breast cancer and a germline BRCA1/2 mutation." (PMID 38170520, 2024).
breast cancer (continued). "Two genes commonly associated with breast cancer are BRCA1, BRCA2 (breast cancer-associated genes), and the HER2 gene (human epidermal growth receptor 2)." (PMID 39877793, 2024). "Recent research demonstrates that individuals harboring BRCA2 mutations have a higher risk of developing male breast cancer, prostate cancer, and pancreatic cancer than those with BRCA1 mutations." (PMID 38255960, 2024). "Recommendations for lowering breast cancer risk in BRCA1/2 mutation carriers include regular surveillance, risk-reducing surgeries and chemoprevention." (PMID 39421188, 2024). "Given that women who have been treated for breast cancer and who carry a BRCA1/2 gene mutation are at a high risk of recurrence, it is plausible that these women are also more likely to display high levels of FCR." (PMID 39192282, 2024). "Breast cancer is indicated explicitly by genomic markers such as breast cancer susceptibility proteins (BRCA1 and BRCA2)." (PMID 39273572, 2024). "This study provides a single-cell atlas of breast tissues of BRCA1/2 mutation carriers and demonstrates that aberrant signaling due to BRCA1/2 mutations is sufficient to initiate breast cancer by mutant PIK3CA." (PMID 38059556, 2024). "Genetic testing for breast cancer predisposing genes has expanded beyond BRCA1 and BRCA2 and now includes panels of 20 or more genes." (PMID 39543654, 2024). "For Korean breast cancer patients, the prevalence of BRCA1/2 mutation for patients with a family history of breast or ovarian cancer is 22.3%, and the cumulative risk of breast cancer is 72.1% for BRCA1 and 66.3% for BRCA2 mutation carriers." (PMID 38254240, 2024). "Analogous to breast cancer patients with BRCA1 mutations, mice bearing Brca1- and Bard1-deficient tumors display remarkable initial responses to PARPi that are inevitably followed by disease progression." (PMID 38956205, 2024). "The lower breast examination rate among BRCA1/2 mutation carriers compared to the general population is concerning, as these individuals have a significantly higher risk of developing breast cancer." (PMID 39590130, 2024). "Hereditary and sporadic BRCA1-associated breast cancers are often triple-negative and express basal markers, such as keratin 14 (K14) and K5." (PMID 38499540, 2024). "The use of PARP inhibitors, such as olaparib and talazoparib, has shown effectiveness in treating breast cancer with BRCA1 or BRCA2 mutations." (PMID 38256428, 2024). "From the perspective of health services in China and the United States, our research results show that talazoparib is cost-effective in treating advanced breast cancer patients with BRCA1/2 mutations in China and the United States." (PMID 38886516, 2024). "PDBID: 4KD7 is associated with breast cancer through its interaction with BRCA1, a well-known tumour suppressor gene, and regulates it." (PMID 38399423, 2024). "Numerous human and mouse studies have looked at NF2-mutations in breast cancers and have found that these tumors indirectly modulate Hippo signaling when simultaneously mutated with BRCA1 and BARD1." (PMID 39796693, 2024). "Risk-reducing bilateral salpingo-oophorectomy (RRSO) is recommended for breast cancer gene 1 (BRCA1) and 2 (BRCA2) mutation carriers." (PMID 38256099, 2024). "BRCA1/2 mutation testing is of significant importance to breast cancer patients for several reasons, as it can impact their treatment decisions and overall management." (PMID 38791944, 2024). "Approximately 84% of hereditary breast cancers and more than 90% of hereditary ovarian cancers are caused by mutations in BRCA1 and BRCA2 genes." (PMID 38256099, 2024). "The patient also had a mutation in the breast cancer susceptibility gene 1 (BRCA1, OMIM: 113705) and tested positive for the progesterone and estrogen receptors." (PMID 39763599, 2024).